PPIA (peptidylprolyl isomerase A)
Diseases named in the same sentence as PPIA in open-access papers (continued):
Sharing a sentence is not in itself a finding about the gene and the disease.
oral epithelial dysplasia (1 paper, 2013). "The data also showed us that the level of PPIA, Prdx6, and CD147 in OSCC was significant higher when compared with oral epithelial dysplasia and/or normal oral mucosa (P<0.05)." (PMID 24386210, 2013).
ovarian serous tumor (1 paper, 2014). A benign, borderline, or malignant epithelial tumor of the ovary characterized by the presence of neoplastic epithelial cells that, in well differentiated tumors, resemble the epithelial cells of the fallopian tube and, in poorly differentiated tumors, show anaplastic features. "ACTB, PPIA, RPL13A, RPLP0, TBP, and B2M achieved high expression stability, which suggested that they were adequate for normalizing gene expression data among ovarian serous tumors." (PMID 24776823, 2014).
pulmonary TB (1 paper, 2025). "To identify the most stable HKGs for analyzing material from patients with pulmonary TB, we selected eight genes—ACTB, B2M, GAPDH, HPRT1, PPIA, RPL13A, YWHAZ and UBC—that are most commonly employed as reference genes in clinical studies." (PMID 41303702, 2025).
schizophrenia (1 paper, 2016). A major psychotic disorder characterized by abnormalities in the perception or expression of reality. "As in our study, lower levels of PPIA mRNA have been reported in the cortex of subjects with schizophrenia." (PMID 27206773, 2016). "In BA 9 there were higher levels of GAPDH (p = 0.03) and SNCA (p = 0.04) in the cortex of subjects with schizophrenia; there was also a trend (p = 0.08) toward higher levels of PPIA mRNA." (PMID 27206773, 2016). "To address this issue we measured levels of mRNA for six potential reference genes (GAPDH, PPIA, SNCA, NOL9, TFB1M and SKP1) in three cortical regions (Brodmann’s areas (BA) 8, 9 and 44) from 30 subjects with schizophrenia and 30 age and sex matched controls." (PMID 27206773, 2016).
tongue cancer (1 paper, 2013). A malignant neoplasm affecting the tongue. "We previously used immunohistochemistry methods to evaluate the prognostic role of members of antioxidant enzymes, overexpression of PPIA, CD147 and thioredoxin 1 were correlated to worse survival in tongue carcinoma." (PMID 24386210, 2013).
infection (146 papers, 2006 to 2026). The state of being infected such as from the introduction of a foreign agent such as serum, vaccine, antigenic substance or organism. "PPIA belongs to a family of immunoaffinity proteins and its secretion is associated with hypoxia, infection, and oxidative stress and has an important role in protein folding, transport, and T-cell activation." (PMID 37714937, 2023). "Cyclophilin A (PpiA) of Mycobacterium tuberculosis is secreted during infection in intraphagosomal niche." (PMID 24505389, 2014). "Since we observed a down-regulation of PPIA before the global cellular shutoff, cyclophilin A may be a target for PrV and play a role in infection via an unknown mechanism." (PMID 18331636, 2008). "Moreover PpiA is also known to be upregulated in intraphagosomal niche during infections." (PMID 28261567, 2017). "Thus, induction of PpiA mediated TNF-α by macrophages at the site of infection permits the multiplication of intracellular bacteria and may therefore present an evasion mechanism employed by M. tb." (PMID 28261567, 2017). "At 24 h post-infection, the mRNA level of TNF-α, IL-1β, and IL-6 were measured by relative quantitative RT-PCR normalized against peptidylprolyl isomerase A (PPIA), a molecule that has been previously used for internal control." (PMID 31561412, 2019). "Due to the attenuated infection, HSV-1 induced host shutoff, as measured by RNA levels of the housekeeping genes POLR1B, SDHA, TBP, and PPIA, which were reduced." (PMID 29089033, 2017). "Although currently there are no gene expression data to claim this but an earlier study wherein PpiA was shown to induce IFN-γ in LTBI as compared to that of PTB suggested enhanced expression of this protein, late in infection cycle." (PMID 28261567, 2017). "As expected, removal of CypA expression by disruption of the PPIA gene with CRISPR technology resulted in efficient HIV-1 A92E infection without the need for CypA inhibition (− CsA/+ CsA infection ratio > 0.8)." (PMID 30947724, 2019).
cancer (115 papers, 2009 to 2026). A tumor composed of atypical neoplastic, often pleomorphic cells that invade other tissues. "Consistent with this and our findings, DepMap Cancer Gene Dependency data show that PPIA/CYPA-KO causes frequent loss of fitness/viability in a panel of MM cell lines (Dataset EV4)." (PMID 38943005, 2024). "Consistent with our findings, DepMap Cancer Gene Dependency data show that PPIA/CYPA-KO causes frequent loss of fitness/viability in a large panel of NBm cell lines (Dataset EV4)." (PMID 38943005, 2024). "Consistent with our findings, DepMap Cancer Gene Dependency data shows that PPIA/CYPA-KO causes frequent loss of fitness/viability in a panel of CML cell lines (Dataset EV4)." (PMID 38943005, 2024). "PPIA has been implicated in a broad range of pathological processes, including inflammatory diseases, aging and the progression of cancer metastasis." (PMID 38355636, 2024). "In summary, PPIA was upregulated in various kinds of human cancer, including GC, and associated with poor prognosis in GC." (PMID 37926757, 2023). "To further investigate the underlying function of the PPIAP22/miR-197-3p/PPIA axis in cancers, we found 3,950 genes were significantly positively correlated with PPIA, while 5,909 genes were significantly negatively correlated." (PMID 33790943, 2021). "PPIA (peptidylprolyl isomerase A) is implicated in multiple human cancers." (PMID 40723891, 2025). "PI3K and MAPK proteins as well as RAC1 BCL2 and PPIA were found to be overexpressed between cancer tissues and healthy controls." (PMID 39409902, 2024). "We also found that high expression of PPIA had a close relationship to clinical parameters of GC patients, including tumor grade, cancer stage, nodal metastasis status, gender, age and so on." (PMID 37926757, 2023). "Among other chaperones, PARK7 (Parkinson protein 7) and PPIA (Peptidylprolyl Isomerase A) are upregulated and secreted by cancer cells." (PMID 37835519, 2023). "An increasing number of studies have proved that Peptidylprolyl isomerase A (PPIA) can play an oncogene role in various cancer types." (PMID 37926757, 2023). "Herein, we reported the high expression of PPIA in pan-cancer, which were partially consistent with Yu’s findings." (PMID 37926757, 2023). "To further validate the expression and clinical significance of the CypA/CD147 axis in a wide range of cancers, we performed gene expression and survival analyses of PPIA and BSG in 24 different tumor types." (PMID 36012604, 2022). "Subsequently, we analyzed the relationship between the cancer stage and the expression levels of PPIA and BSG using UALCAN." (PMID 36012604, 2022). "Under the conditions of this experiment, the combinations of two suitable internal reference genes of cancer esophageal tissues, normal esophageal tissues, and all samples were PPIA and RPS18." (PMID 36467891, 2022). "To obtain an optimal standardization, we first compared the expression level of the four common housekeeping genes GAPDH, β-actin, B2M, and PPIA in twenty selected cancer and normal colon tissue samples." (PMID 33917056, 2021). "PPIA overexpression is reported in various cancer types, its expression influenced by chemotherapy and PPIA is a reported target gene of dysregulated miRNA species present in GBM patient plasma." (PMID 32635403, 2020). "PPIA, a further gene down-regulated by O. regalis extract and coding for Cyclophilin A, has been related to tumor progression and/or metastasis of a variety of cancer types." (PMID 29202741, 2017). "PPIA has also been shown to have significant potential for reversal of platinum chemoresistance and found to be up-regulated in various human cancers with a strong correlation to malignant transformation in several types of cancers." (PMID 29132396, 2017).
cancer (continued). "Little is known about PPIC in cancer, however PPIA and another PPIase PIN1 have been shown to interact with key growth and signalling proteins including cyclin D1, CDK10, cdc27, and PLK1, with diverse downstream effects on MAPK signalling." (PMID 27852308, 2016). "Both of PPIA and CD147 are highly expressed in cancer cells and associated to promoting cancer invasiveness and chemoresistance." (PMID 24386210, 2013). "A review on the selection of normalizers for RT-qPCR cancer studies recommended that a combination of PPIA and ACTB, HPRT1 (hypoxanthine phosphoribosyltransferase 1), TBP (TATA-binding protein), or GAPDH, or an appropriate combination of three of these genes, should be employed." (PMID 40943534, 2025). "Notably, PPIA-BSG and LTB-LTBR have been linked to a positive correlation in various cancers and are associated with poor prognosis." (PMID 39013860, 2024). "Herein, the expression levels of PPIA in pan-cancer were analyzed." (PMID 37926757, 2023). "Moreover, among the differentially expressed signals, Peptidylprolyl Isomerase A (PPIA, 1505.8 m/z), which has already demonstrated a role in the development of cancer, was found overexpressed in NIFTP RAS-mutated nodules compared to wild-type lesions." (PMID 36768889, 2023). "PPIA belongs to the immunophilin family and is involved in the anti-apoptotic cancer cell." (PMID 36134033, 2022). "Therefore, changes in expression of PPIA are highly related to inflammatory disorders and cancers." (PMID 35507843, 2022). "Additionally, involvement of multifunctional protein PPIA in cancer progression has been described." (PMID 23443080, 2012). "The prototypical cyclophilin family member, cyclophilin-A (PPIA), was initially discovered as the intracellular target of cyclosporin-A over a quarter century ago, yet only recently have the extracellular roles of PPIA in inflammatory disorders and in driving dozens of cancers emerged." (PMID 22631225, 2012). "In an in vivo murine cancer model studied by Northern blot analysis, all three HKGs, i.e., ACTB, PPIA, and GAPDH, were found to be significantly upregulated in hepatoma cells compared to adjacent normal liver tissue." (PMID 40943534, 2025). "Our results support a TNBC model whereby in older cohorts, myeloid cells and CAFs interact with cancer basal cells via LGALS9/P4HB, PPIA/BSG and PLAU/PLAUR signaling to promote EMT and cell motility." (PMID 41188599, 2025). "Conversely, the six downregulated genes (SERPINE1, TNFRSF12A, PHLDA1, RNASEK, PPIA, and G0S2) are involved in diverse cancer-related pathways." (PMID 40340807, 2025). "In this study, we discovered that PPIA modulates NRF2 stability, and its prolyl cis-trans isomerase activity renders cancer progression of NRF2-hyperactivated NSCLC." (PMID 38830868, 2024). "In the older TNBC cohort, myeloid cells and CAFs interact with cancer basal cells through LGALS9/P4HB, PPIA/BSG, and PLAU/PLAUR ligand/receptor pairs to promote EMT and cell motility, as confirmed by the age-related increase in EMT ARPs." (PMID 39483921, 2024). "Peptidyl-prolyl isomerase A/cyclophilin A (PPIA/CYPA) has been reported as overexpressed in BC, promoting cell survival, cancer cell growth, malignant transformation, metastasis, drug resistance, anti-apoptosis, and EMT in NSCLC cells via p38 MAPK." (PMID 36500393, 2022). "The expression of PPIA and BSG was positively correlated in all 22 tumor types analyzed, indicating that the CypA/CD147 interaction plays a crucial role in cancer development." (PMID 36012604, 2022). "In contrast to PPIA, nucleophosmin (NPM1) showed a higher biotinylation ratio in HEK-293T cells than in the HCT-116 cancer cell line." (PMID 33799492, 2021). "Whereas the Ct-values between cancer and normal colon tissues varied by about three cycles for GAPDH, β-actin, and PPIA, they were almost identical for B2M (20.20 vs. 20.04)." (PMID 33917056, 2021).
cancer (continued). "Of the eight housekeeping genes studied, peptidylpropyl isomerase A (PPIA also called cyclophilin A) and ribosomal protein S13 (RPS13), especially in combination, were best suitable to normalize gene expression in cancer and normal tissue." (PMID 25750709, 2015). "In addition, PPIA is known to regulate transcription factor NFAT, which plays important roles in cancer progression." (PMID 38830868, 2024). "Plasminogen activator, urokinase (PLAU) and cyclophilin A (PPIA), which promote EMT in tumor cells and fibrosis in CAFs34–36, were enriched in signaling nodes between myCAFs:cancer cells and monocyte/macrophages:cancer cells in the older cohort, supporting the EMT ARPs previously observed." (PMID 39483921, 2024). "Moreover, the plasminogen activator-urokinase (PLAU) and cyclophilin A (PPIA) signaling nodes, which promote EMT in tumor cells and fibrosis in CAFs35–37, were enriched between cancer epithelial cells (receptors) and both monocyte/macrophage and CAFs (ligands) in the older cohort." (PMID 41188599, 2025). "Indeed, PPIA mRNA expression across a panel of cancer cells did not correlate with sensitivity to RMC-7977." (PMID 38589574, 2024). "In addition, we evaluated whether PPIA, PPIB or PPIL3 could be correlated with cisplatin sensitivity in liver tissue-derived cancer cell lines." (PMID 36230472, 2022). "Furthermore, the expression of PPIA and BSG was positively correlated in many cancers." (PMID 36012604, 2022). "However, GAPDH, ACTB, and PPIA have not been included in the census of human cancer genes." (PMID 40943534, 2025).
tumor (109 papers, 2007 to 2026). "CellChat analysis uncovered a cyclophilin (PPIA/PPIB)-dependent tumor-stroma signaling axis that positions BSG/CD147 as the key mediator for intercellular communication between tumor hepatocytes, fibroblasts and T cells." (PMID 41646335, 2026). "According to the immunohistochemical staining of paired tumor/normal tissues, PPIA and NRF2 expression were dramatically higher in NSCLC specimens than in adjacent normal lung tissues." (PMID 38830868, 2024). "Evident by comparison to their cognate normal tissue analogs, discernible upregulation was registered across a slew of tumor tissues for PPIA, TRAF2, TRIM28, and HGS." (PMID 38460947, 2024). "Of note, tumor tissue microarray and bioinformatics analysis indicated that PPIA and NRF2 are vastly upregulated in patients with NSCLC." (PMID 38830868, 2024). "In contrast, high expression of EIF3E and PPIA were involved in lipid metabolism pathways, and they were also reported to take part in the proliferation of tumour cells." (PMID 37491740, 2023). "To validate the clinical significance of the CypA/CD147 interaction, we analyzed the expression levels of PPIA and BSG genes encoding CypA and CD147, respectively, in a wide range of tumor types using The Cancer Genome Atlas (TCGA) database." (PMID 36012604, 2022). "PPIAP22 and PPIA mRNA expression levels were also significantly higher in tumor tissues than in normal tissues (p < 0.0001)." (PMID 33790943, 2021). "To further investigate the function of the PPIAP22/miR-197-3p/PPIA axis in tumor immunity, we analyzed the expression of PPIA and immune cell infiltration in HCC then by using TIMER." (PMID 33790943, 2021). "We also analyzed the correlation between expression of PPIAP22 or PPIA and clinicopathologic features, including gender, age, tumor size, number of tumors, metastasis, and TMN stages." (PMID 33790943, 2021). "ACTB and cyclophilin A (PPIA) expression in human tumor cell lines also varied widely after hypoxia treatment." (PMID 25881111, 2015). "Taking our findings together, we recommend HPRT1 and PPIA as the best reference genes for relative quantification in gene expression studies comparing normal and tumor endometrial tissues." (PMID 25473950, 2014). "Altogether, our results revealed that PPIA might be participated in anti-tumor immunity progression and mediated immune evasion in GC." (PMID 37926757, 2023). "Cell division control protein 42 homolog (CDC42), GSTP1, and peptidyl-prolyl cis-trans isomerase A (PPIA) were associated with regulation of the stress-activated mitogen activated protein kinase (MAPK) cascade, which were closely related to the tumor cell proliferation." (PMID 37124724, 2023). "Analysis of these data, in combination with our results, suggest that PPIA may play a tumor promoting role in GC." (PMID 37926757, 2023). "According to tumor grade, an increased expression level of PPIA was observed in gastric patients." (PMID 37926757, 2023). "While not previously associated with astrocytes, peroxiredoxin‐1 (PRDX1) is an intracellular enzyme with antioxidant activity reported to be secreted by tumor cells; and prolyl isomerase (PPIA), although cytoplasmic, is secreted as a defense mechanism in response to oxidative stress." (PMID 37303123, 2023). "However, no statistical difference was found between the expression of CDC37L1 or PPIA and the patients’ age, gender, grading, and tumor size and recurrence." (PMID 35760798, 2022). "Our findings demonstrate that the PPIAP22/miR-197-3p/PPIA axis plays a vital role in the progression of HCC by increasing the malignancy of tumor cells and regulating the immune cell infiltration, especially macrophage, through CCL15-CCR1 or CXCL12-CXCR4/CXCR7 pathways." (PMID 33790943, 2021). "PPIA was also reported to participate in tumor proliferations and invasions." (PMID 32592319, 2020). "This suggests that PPIA may act as an important oncogene in 15 tumor types." (PMID 37926757, 2023).